STAT5A (signal transducer and activator of transcription 5A)
Diseases named in the same sentence as STAT5A in open-access papers (continued):
Sharing a sentence is not in itself a finding about the gene and the disease.
autoimmune disease (3 papers, 2007 to 2022). A disorder resulting from loss of function or tissue destruction of an organ or multiple organs, arising from humoral or cellular immune responses of the individual to their own tissue constituents. "Stat5a-deficient mice were reported to lose tolerance, resulting in the development of autoimmune diseases." (PMID 17244351, 2007). "Indeed, mice deficient in JAK3 or STAT5A/B develop a severe immunodeficiency that is followed by multiple organ autoimmune diseases, a decreased number or the absence of CD4+CD25+ nTreg in their peripheral lymphoid organs, and early death." (PMID 21647403, 2011). "All STAT family members (STAT1, STAT2, STAT3, STAT4, STAT5A, STAT5B, and STAT6) are related to autoimmune diseases." (PMID 35204186, 2022). "Indeed, mice deficient in IL-2, IL-2R, JAK-3, or STAT5A/B have an absent or reduced number of thymic and peripheral CD4+ CD25+ nTreg and consequently develop multiple organ autoimmune diseases." (PMID 21647403, 2011).
bladder cancer (3 papers, 2019 to 2025). "In our previous work, we systematically analyzed STAT5A expression across 42 cancer types, revealing its dualistic prognostic impact: elevated STAT5A levels were associated with favorable survival outcomes in breast and bladder carcinomas but with a poorer prognosis in hematologic malignancies." (PMID 41301421, 2025).
colitis (3 papers, 2018 to 2023). Inflammation of the colon. "In the intestinal epithelium, deficiencies in STAT1, STAT3, or STAT5A did not lead to spontaneous inflammation, even though these mice were prone to chemical‐induced colitis." (PMID 29941542, 2018).
ductal carcinoma in situ (3 papers, 2007 to 2022). "This is in line with recent findings showing that breast lesions with aberrantly proliferating cells like atypical ductal hyperplasia, ductal carcinoma in situ and invasive carcinomas are characterized by a reduction or absence of STAT5a expression." (PMID 17651480, 2007).
Insulin resistance (3 papers, 2016 to 2020). Increased resistance towards insulin, that is, diminished effectiveness of insulin in reducing blood glucose levels. "The increased PTPN1 and STAT5A in the lymphocytes of umbilical core blood in GDM mothers are proposed to contribute to offspring insulin resistance." (PMID 29088862, 2017). "The STAT5A-mediated induction of pyruvate dehydrogenase kinase 4 expression by prolactin results in an inhibition of insulin-stimulated glucose transport in fat cells and contributes to insulin resistance." (PMID 29088862, 2017). "Since PTPN1 and STAT5A were demonstrated to impair insulin signaling, MCAT and its network may be novel mechanisms as to the offspring insulin resistance affected by intrauterine hyperglycemia." (PMID 29088862, 2017). "Besides PTPN1 and STAT5A, some other genes like FASN, TAP1, which are also involved in insulin resistance, have close relationship with MCAT." (PMID 29088862, 2017).
invasive carcinoma (3 papers, 2007 to 2021). A carcinoma that is not confined to the epithelium, and has spread to the surrounding stroma. "For this study, specimens previously shown to have ADH, DCIS, or invasive carcinoma only minimally expressing STAT5a (mean immunoscores 1.0–1.2) were examined for PRLR." (PMID 21655368, 2008). "In DCIS and invasive carcinoma, reverse expression occurs in normal cells, causing an increase in PRLR and a decrease in STAT5a, which might indicate a disturbance in the signalling pathway that may be associated with carcinogenesis." (PMID 34651424, 2021). "A previous study showed that STAT5a expressed in majority of normal breast epithelial cells, but not generally in carcinoma in situ or invasive carcinoma, except in those secretory carcinomas that maintain STAT5a." (PMID 34651424, 2021). "Reversal of the expression seen in normal cells in DCIS and invasive carcinoma, resulting in increased PRLR and decreased STAT5a, may indicate a signaling pathway disturbance and possibly a divergence related to carcinogenesis." (PMID 21655368, 2008). "STAT5a was previously found to be expressed in most normal breast epithelial cells but not in many in situ or invasive carcinomas except secretory carcinomas which retain STAT5a expression." (PMID 21655368, 2008).
lung adenocarcinoma (3 papers, 2022 to 2024). A carcinoma that arises from the lung and is characterized by the presence of malignant glandular epithelial cells. "In multiple myeloma cells, YTHDF2 sustains proliferation through the STAT5A/MAP2K2/p-ERK pathway, while in lung adenocarcinoma cells, it promotes proliferation by targeting the AXIN1/WNT/β-catenin signalling pathway." (PMID 38397033, 2024).
multiple myeloma (3 papers, 2024). "A previous study showed that YTHDF2 can recognize STAT5A and mediate its degradation in multiple myeloma." (PMID 38879589, 2024). "It has been reported that YTHDF2 recognizes m6A-modified STAT5A and promotes its mRNA degradation in multiple myeloma." (PMID 38879589, 2024). "YTHDF2 was identified to promote multiple myeloma cell proliferation via STAT5A/MAP2K2/p-ERK axis." (PMID 37256443, 2024).
non-small cell lung carcinoma (3 papers, 2014 to 2023). A group of at least three distinct histological types of lung cancer, including non-small cell squamous cell carcinoma, adenocarcinoma, and large cell carcinoma. "SGK1, identified in our study as a target gene of both STAT5A and STAT5B, has also been implicated in the pathophysiology of non-small-cell lung cancer and adrenocortical tumors in humans, although this has not been reported in rodents." (PMID 24497979, 2014). "The aim of the present study was to evaluate the relationship between STAT5A/B, COX-2, and PIAS3 mRNA expression and tumor staging, metastasis status, and histopathological subtype in 71 patients with confirmed non-small cell lung cancer (NSCLC) diagnosis." (PMID 25137041, 2014).
Obesity (3 papers, 2016 to 2017). Accumulation of substantial excess body fat. "Mice that lack Stat5a/b in the central nervous system (Stat5NKO mice) develop severe obesity, accompanied by hyperphagia, hyperleptinemia, impaired thermal response to the cold, and insulin resistance." (PMID 29259155, 2017). "Our previous in vivo research found that both male and female mutant mice, whose Stat5a/b loci in the CNS were deleted (Stat5NKO), developed severe obesity, accompanied by hyperphagia, hyperleptinemia, impaired thermal response to the cold, and insulin resistance." (PMID 28806763, 2017).
osteosarcoma (3 papers, 2011 to 2022). A usually aggressive malignant bone-forming mesenchymal neoplasm, predominantly affecting adolescents and young adults. "Patients with osteosarcoma with a low STAT5A expression show a poor prognosis." (PMID 36157228, 2022).
prostate tumor (3 papers, 2013 to 2018). "Similar to the presence of nuclear Stat5a/b protein in specific areas of prostate tumor, Stat5a/b locus amplification was dispersed into groups of PC cells within the tumor tissue, as demonstrated by FISH of paraffin-embedded tissue sections." (PMID 27741508, 2017).
T-cell lymphoma (3 papers, 2015 to 2021). "66.7% of cases had mutations in genes of the JAK-STAT signaling pathway which was known as a major oncogenic mechanism in T cell lymphomas, including STAT5B mutations (4/9), JAK3 mutations (3/9), and STAT5A mutations (2/9)." (PMID 34895266, 2021). "Although a reciprocal regulatory relationship was established between STAT5A and a NPM–ALK fusion protein in T-cell lymphoma, no direct connection between STAT5 and wild-type NPM1 has been documented." (PMID 28005077, 2016).
anaplastic large cell lymphoma (2 papers, 2022 to 2024). Anaplastic large cell lymphoma (ALCL) is a rare and aggressive peripheral T-cell non-Hodgkin lymphoma, belonging to the group of CD30-positive lymphoproliferative disorders, which affects lymph nodes and extranodal sites. "Furthermore, STAT5 activation is targetable in cutaneous T cell lymphomas, bearing STAT5A and STAT5B copy number gains, and PDGFRβ-driven anaplastic large cell lymphoma." (PMID 38618957, 2024).
breast adenocarcinoma (2 papers, 2012 to 2020). "Second, cytoplasmic or nuclear Stat5a was detected in 17% of 30 cases of breast adenocarcinomas compared with nearly 100% positive expression in normal tissue." (PMID 23036105, 2012). "Other groups reported high frequencies of nuclear Stat5a expression in breast adenocarcinomas, ranging from 48% to 74% of cases." (PMID 23036105, 2012). "In addition, STAT5a-regulated NOX5-L expression increased the invasion and migration of human SK-BR-3 breast adenocarcinoma cells and the inhibition of STAT5a by N-α-acetyltransferase protein (Naa10p) led to the suppression of cell motility and invasion in human MCF-7 and MDA-MB-231 BCa cells." (PMID 32633727, 2020).
Burkitt lymphoma (2 papers, 2017). A rare form of malignant mature B-cell non-Hodgkin lymphoma. "AML and Burkitt lymphoma cell lines expressed STAT5A to lower extent, but showed high levels of O-GlcNAc as detected by WGA." (PMID 28074064, 2017).
COVID-19 (2 papers, 2021 to 2024). A disease caused by infection with severe acute respiratory syndrome coronavirus 2. "Epigenes that participate in the immune response through different mechanisms (response to interferon or NF-kB complex) are among the main genes identified and are evident drug target candidates for COVID-19 because they already have associated drugs targeting them (such as STAT5A and STAT1)." (PMID 34031419, 2021). "Interestingly in ILC1 cells, ICAM1, PIK3AP1, STAT5A, TGFB1 and FAM65B genes show the highest degree of network rewiring across healthy vs COVID-19 correlation networks." (PMID 39026668, 2024).
head and neck carcinoma (2 papers, 2007 to 2022). A carcinoma that arises from the head and neck region. "Inhibition of STAT5b, but not of STAT5a, in xenograft models of head and neck carcinomas via antisense oligonucleotides repressed tumor growth and hindered expression of the STAT5-regulated genes cyclin D1 and Bcl-XL." (PMID 17997837, 2007).
immune deficiency (2 papers, 2018 to 2019). "Interestingly, in mouse models, severe growth restriction and immune deficiency were observed only in the knock-out of both the Stat5b and Stat5a genes, but expression of normal Stat5a/b as low as ~10% significantly reduced the severity of immunodeficiencies." (PMID 29844444, 2018). "Loss-of-function (LOF) mutations in STAT5B led to human primary immune deficiencies affecting NK cells —so far not reported for STAT5A." (PMID 31690038, 2019).
invasive ductal carcinoma (2 papers, 2008 to 2012). "Combined with the over-expression of PRLR, lack of detectable STAT5a in the nuclei of in situ and invasive ductal carcinoma suggests the possibility of attempted STAT5a activation that has been inhibited." (PMID 21655368, 2008).
lymphoid neoplasm (2 papers, 2019 to 2023). A neoplasm composed of a lymphocytic cell population which is usually malignant (clonal) by molecular genetic and/or immunophenotypic analysis. "To dissect the individual contribution of STAT5A and STAT5B to lymphoid tumor formation, we injected Stat5a−/−, Stat5b−/−, or wt BCR/ABLp185+ cell lines subcutaneously into NSG mice." (PMID 30679796, 2019).
myeloid leukemia (2 papers, 2015 to 2019). A clonal proliferation of myeloid cells and their precursors in the bone marrow, peripheral blood, and spleen. "In BCR/ABL-driven lymphoid as well as myeloid leukemia, the combined loss of STAT5A and STAT5B halts disease, the requirement for STAT5A/B extending to the leukemic stem cell compartment." (PMID 30679796, 2019). "Our results reveal important structural aspects of cytoplasmic pSTAT5A found in myeloid leukemias and will contribute to the understanding of STAT5A mediated cytoplasmic signaling." (PMID 25885255, 2015). "These processes are dominant over the BCR-ABL induced nuclear accumulation of STAT5A and therefore give a rational explanation for the cytoplasmic localization of STAT5A in a number of myeloid leukemias." (PMID 25885255, 2015). "While mechanistic details of this crosstalk remain elusive, constitutively active STAT5A (STAT5AS710F) was found in a complex with Gab2, which promotes the cytoplasmic localization of the persistently phosphorylated transcription factor in myeloid leukemias." (PMID 25885255, 2015).
myeloproliferative disease (2 papers, 2008 to 2019). "As with STAT3, genetic alterations in the STAT5A gene has been implicated in myeloproliferative disorders and linked to hematopoietic stem cell proliferation." (PMID 31783691, 2019). "It has been shown that both oncogenic Ras and STAT5 can induce myeloproliferative disease, yet adult hematopoiesis appears normal in STAT5A/B-deficient mice." (PMID 18577264, 2008).
myocardial infarction (2 papers, 2018 to 2021). Gross necrosis of the myocardium, as a result of interruption of the blood supply to the area, as in coronary thrombosis. "In rat and human MSCs derived from bone marrow, miR-211 overexpression could rescue the aging-impaired migration, and thus increase retention and enhance therapeutic effects in a rat myocardial infarction model, via targeting STAT5A." (PMID 29734654, 2018). "In the LAD ligation of a rat model, as early as 5 minutes after myocardial infarction, we observed JAK2, STAT1, STAT3, STAT5a, and STAT6 phosphorylation." (PMID 34516361, 2021).
osteoporosis (2 papers, 2018 to 2022). A condition of reduced bone mass, with decreased cortical thickness and a decrease in the number and size of the trabeculae of cancellous bone (but normal chemical composition), resulting in increased fracture incidence. "STAT5A deletion in an osteoporosis model related to murine age has been shown to lead to substantially reduced loss of bone." (PMID 35517418, 2022). "We found that Stat5a deletion reversed age-related reductions in bone mass and BMD in 40-week-old mice, suggesting that Stat5a deletion had a protective effect against age-related osteoporosis." (PMID 30429452, 2018).
pancreatic cancer (2 papers, 2017 to 2019). "STAT5A, TRAF6 are over-expressed in pancreatic cancer cells resistant to gemcitabine." (PMID 29023490, 2017).
sarcopenia (2 papers, 2022 to 2024). Progressive decline in muscle mass due to aging which results in decreased functional capacity of muscles. "Our results suggested that BDNF, JAK2, RhoC, Myh6, Stat5a, Tnnc1, and other genes may mediate the beneficial effects of exercise on sarcopenia through these pathways." (PMID 39309455, 2024). "Transcriptomic analysis identified BDNF, JAK2, RhoC, Myh6, Stat5a, and Tnnc1 as core target genes that may mediate the effects of different exercise intervention stimuli through the JAK-STAT, cGMP-PKG, and Rap1 pathways to improve the skeletal muscle phenotype of sarcopenia." (PMID 39309455, 2024).
spinal muscular atrophy (2 papers, 2012 to 2024). A motor neuron disease that affect the muscles, and characterized by muscle weakness and atrophy resulting from progressive degeneration and irreversible loss of the anterior horn cells in the spinal cord (i.e., lower motor neurons) and the brain stem nuclei. "Over-expression of STAT5A reduces neuronal degeneration associated with spinal muscular atrophy, a neurodegenerative disease with similar pathogenesis as ALS, and it provides oligodendrocyte protection, which in turn favors neuronal environment preservation." (PMID 23300739, 2012). "In a mouse model of severe spinal muscular atrophy, murine skeletal muscle growth and fiber composition were regulated via the transcription factor STAT5a/b, linking growth hormone to the androgen receptor." (PMID 39309455, 2024).
viral infections (2 papers, 2020 to 2025). "The Human T-cell Leukemia Virus 1 Infection pathway involved genes such as STAT5A and IL2RB, highlighting a heightened immune response against viral infections." (PMID 40621499, 2025). "In the present study, our findings revealed for the first time that STAT5a, but not STAT5b, regulated the expression of key factors involved in the immune response after virus infection." (PMID 33317444, 2020).
adenosis (1 paper, 2008). "The cells of usual ductal hyperplasia and microglandular adenosis also expressed STAT5a and internal controls of adipose tissue, endothelial cells, and lymphocytes always showed reactivity." (PMID 21655368, 2008).
Airway obstruction (1 paper, 2013). Obstruction of conducting airways of the lung. "However, the gain-of-function of this signal transducer in mice that carry Stat5a/b hypomorphic alleles resulted in abnormally high numbers of circulating granulocytes that caused severe airway obstruction." (PMID 23565285, 2013).
Arrhythmia (1 paper, 2025). Any cardiac rhythm other than the normal sinus rhythm. "Patients with heart failure demonstrated a significantly lower median SFRP5 concentration relative to patients with arrhythmias, with insignificant differences regarding WNT5a and STAT5A expressions between patients with different cardiac diseases." (PMID 41465371, 2025).
atherosclerosis (1 paper, 2023). A disease characterized by the build-up of fatty material and calcium deposition in the arterial wall resulting in partial or complete occlusion of the arterial lumen. "In summary, we identify STAT5A as an important determinant of macrophage functions and inflammation in the context of atherosclerosis and show its promise as therapeutic target in human atherosclerotic plaque inflammation." (PMID 37920458, 2023). "Considering the role of lipid uptake and phagocytosis in atherogenesis, these functional changes induced by STAT5A silencing might strongly impact the initiation and transition from stable to unstable plaques in atherosclerosis." (PMID 37920458, 2023). "Next, we examined the expression of STAT5A and STAT5B isoforms in human atherosclerosis." (PMID 37920458, 2023).
atopic dermatitis (1 paper, 2022). "STAT5A SNP rs16967637 was also found to exacerbate the severity of atopic dermatitis in African Americans, whereas STAT5B SNP rs9900213 was found to increase the risk of atopic dermatitis in European Americans." (PMID 36232600, 2022).
autoimmune thyroiditis (1 paper, 2012). "Further experiments will have to show whether indeed the course of murine experimental autoimmune thyroiditis is aggravated in transgenic mice lacking STAT5a/b expression in the thyroid gland." (PMID 22527947, 2012).
Autoimmunity (1 paper, 2020). The occurrence of an immune reaction against the organism's own cells or tissues. "STAT5A/5B-deficient mice show loss of tolerance and autoimmunity in multiple organs." (PMID 32938830, 2020).
B-cell lymphomas (1 paper, 2025). "STAT5A is frequently implicated in oncogenic processes, particularly in breast and hematologic cancers, whereas STAT5B more consistently associates with favorable survival outcomes in epithelial tumors and B-cell lymphomas." (PMID 41301421, 2025).
benign prostatic hyperplasia (1 paper, 2017). A non-cancerous nodular enlargement of the prostate gland. "We observed a strong nuclear immunoreactivity for STAT3 and STAT5A in 93% (n=14/15) and 80% (n=12/15) of CRPC cases, respectively, compared with benign prostatic hyperplasia (BPH)." (PMID 29156772, 2017).
bladder tumors (1 paper, 2010). "For four of these loci (FRZB, STAT5A, KRT13, and HOXB2), bisulfite pyrosequencing assays were able to be designed, and were used to confirm the array findings in a subset of bladder tumors examined on the array." (PMID 20808801, 2010).
Cirrhosis (1 paper, 2006). A chronic disorder of the liver in which liver tissue becomes scarred and is partially replaced by regenerative nodules and fibrotic tissue resulting in loss of liver function. "A small set of genes (ISG20, IFI16, TRIM22, STAT5A) were also highly up-regulated in nearly all samples, including ethanol-cirrhotic livers, suggesting these may play a role in an inflammatory response related to cirrhosis development regardless of etiology." (PMID 17121680, 2006).